TRPM7 (transient receptor potential cation channel subfamily M member 7)
Diseases named in the same sentence as TRPM7 in open-access papers (continued):
Sharing a sentence is not in itself a finding about the gene and the disease.
cancer (continued). "Accumulating evidence has shown that TRPM7 is aberrantly expressed and/or activated in human cancers." (PMID 36230965, 2022). "TRPM7 not only influences the directional navigation of cancer cells but also provides cells with plasticity to counter elevated hydraulic resistances." (PMID 36158191, 2022). "In xenografts, immunodeficient Rag2−/−IL2rg−/− mice, harboring human MDA‐MB‐231 cells, these high TRPM7 levels were required for cancer proliferation and metastasis." (PMID 36844925, 2022). "For example, in prostate cancer, the upregulation of TRPM7 enhanced the migration and invasion potential of cancer cells by promoting epithelial–mesenchymal transition (EMT) process." (PMID 36064388, 2022). "Consistent with the existing data, growing evidence indicates that calcium signaling dysregulation by TRP channels such as TRPM7 drives cancer growth, metastasis, and resistance to chemotherapeutics, including cisplatin." (PMID 35771152, 2022). "In recent years, several studies reporting that TRPM7 plays an important role in carcinogenesis and claim that it can be considered as a potential target in the treatment of various cancers have attracted attention." (PMID 34938330, 2021). "Through its varied physiological roles, TRPM7 is of major importance in many human pathologies including various cancers, such as the pancreas, lungs, stomachs, melanoma, prostate and breast." (PMID 34944940, 2021). "Based on these studies, therapeutic strategies with anti TRPM7 drugs have been designed in cancer patients." (PMID 34312420, 2021). "Since TRPM7 is a key checkpoint and regulator of the activity of some terpenoids against cancer, we also examined the TRPM7 expression level upon oridonin treatment." (PMID 34285910, 2021). "Additional studies have demonstrated that TRPM7 is aberrantly expressed in human diseases such as cancer." (PMID 34901284, 2021). "TRPM7 is required for early embryonic development and is abnormally overexpressed in various cancer cells." (PMID 34627839, 2021). "Previously it was reported that downregulation of TRPM7 in human cancer cells impairs cell proliferation, migration, and invasion." (PMID 34627839, 2021). "Depending on cellular levels of MDMX and TRPM7 as well as other proteins involved in zinc homeostasis, therapeutic strategies and zinc supplementation guidelines have potential for development as cancer therapeutics, diagnosis, or prevention." (PMID 34627839, 2021). "The TRPM7 ion channel will be involved in several cellular processes in cancer such as viability, cell adhesion or migration and apoptosis." (PMID 34944940, 2021). "There are studies related to the effects of TRPM7 expression on cellular proliferation and migration in various cancer cell lines." (PMID 34938330, 2021). "In cancer cells, TRPM7 functions to promote survival, cell cycle progression, migration, growth, proliferation, invasion, and epithelial-mesenchymal transition (EMT)." (PMID 34901284, 2021). "Some Ca2+-permeable channels have been implicated in the enhanced migration of various cancers: TRPC1, TRPM7, TRPM8, TRPV1, TRPV2, TRPV6, STIM1, Ca2+-release activated Ca2+ modulator 1 (Orai1) and some types of VGCCs." (PMID 36046118, 2021). "We observed higher TRPM7 expression in malignant CMTs than in benign CMTs, indicating that TRPM7 is involved in cancer progression." (PMID 33617107, 2021). "TRPM7 is known to play a key role in tumor progression by regulating cellular proliferation, migration, and invasion in various cancer cell lines." (PMID 34938330, 2021). "Among them, studies have found that a Ca2+, Mg2+, and Zn2+ permeable channel, the melastatin-like transient receptor potential 7 (TRPM7) channel, is aberrantly expressed and plays a role in cancers." (PMID 33435261, 2021). "There are various in vitro studies on the importance of TRPM7 expression in many malignant tumor cell lines." (PMID 34938330, 2021).
cancer (continued). "TRPM7 is one of the key molecules in the regulation of i-Ca2+ levels and has important roles in cancer development, progression, and metastatic cascades." (PMID 34938330, 2021). "For example, in glioma cells, TRPM7 mediated the inhibition of lidocaine toward cancer cell proliferation." (PMID 33435261, 2021). "TRPM7 also affects the activity of cancer cells, and it is involved in Ca2+ and Mg2+ steady-state ion channels." (PMID 34950031, 2021). "Since Ca2+ is an important regulator of cell cycle and proliferation, TRPM7 regulation is considered to be critical to the biological function of cancer cells." (PMID 32907556, 2020). "As TRPM7 is highly involved in many types of cancers, research onTRPM7 related mechanisms is actively underway." (PMID 32907556, 2020). "For example, the Ca2+ current induced by TRPM7 was often found to be potentiated in cancer cells, which is responsible for the development of Vacquinol-1 resistance in glioma cell lines." (PMID 32643506, 2020). "TRPM7 expression is elevated in ovarian, pancreatic, bladder, and breast cancers, with high expression correlated with tumour growth, metastasis, and poor prognosis." (PMID 32825277, 2020). "In general, TRPM7 has a variety of functions in cancer cells including survival, cell cycle progression, proliferation, growth, migration, invasion, and EMT." (PMID 32643506, 2020). "TRPM7 generally affects the growth of many types of cells, including bone cells, muscle cells, and many other cancer cell lines." (PMID 31947967, 2020). "The divalent cation-selective channel transient receptor potential melastatin 7 (TRPM7) channel was shown to affect the proliferation of some types of cancer cell." (PMID 31947967, 2020). "Corroborating our findings others showed that in cancer cells EGF influences Ca2+ in a TRPM7-independent manner probably through other TRP channels." (PMID 32706027, 2020). "The data suggest that TRPM7 (also known as LTRPC7, ChaK1 and TRP-PLIK) is aberrantly expressed in cancer cells and plays a crucial role in cancer, implying a role for TRPM7 as a molecular biomarker and a therapeutic target in human malignancies." (PMID 31947967, 2020). "Arguably one of the most studied and potentially important of these stretch-activated Ca2+ channels involved in migration in non-cancer cells is TRPM7." (PMID 32825277, 2020). "TRPM7 has been shown to affect the proliferation through multiple ways in different kinds of cells such as lymphocyte, cancer cells and endothelial cells." (PMID 32643506, 2020). "These all increase the difficulty to study the specific roles of TRPM7 in cancer cell proliferation." (PMID 31947967, 2020). "TRPM7 has been linked with EMT in ovarian and bladder cancers, the former by calcium-dependent regulation of the PI3K/AKT pathway, and appears to regulate transforming growth factor-β (TGFβ)-induced cell migration and EMT in prostate cancer cells." (PMID 32825277, 2020). "TRPM7 has involved in a variety of cellular functions and critically participates in various diseases mainly including cancer and neurodegenerative disorders." (PMID 32643506, 2020). "Increased evidence has shown that TRPM7 members play an important role in cellular processes, embryonic development, and human disease, especially in cancer." (PMID 30997980, 2019). "It is well known that the function of ion channels, such as transient receptor potential melastatin 7 (TRPM7), is one of the important factors to determine the levels of [Ca2+]i and regulates the development, progression and metastasis of cancer." (PMID 30819230, 2019). "The effects of TRPM7 in pathologic cell differentiation has been intensively investigated in cancer cells, including pancreas, ovary, breast and adenocarcinoma of lungs and prostate." (PMID 30995736, 2019). "A regulatory role of TRPM7 in MAPK signaling has also been observed using pharmacological approaches in cancer tissue and cell lines." (PMID 30995736, 2019).
cancer (continued). "A similar role of TRPM7 in cancer cell migration was found in a number of other tumors such as nasopharyngeal carcinoma and ovarian cancer." (PMID 29772843, 2018). "TRPM7 was aberrantly expressed in the cancer tissues and SPCA-1, NCI-H520, SK-MES-1, A549 and 95D cell lines." (PMID 30477473, 2018). "The prominent role of TRPM7 channels in cancer progression and cancer cell migration has already been discussed (see “TRP channels in cancer cell migration and invasion”)." (PMID 29772843, 2018). "Altogether, our data show that CLIC1 secreted by cancer cells via extracellular vesicles, modulates the activity of neighboring endothelial cells in a TRPM7 dependent manner, promoting tumor angiogenesis." (PMID 30279961, 2018). "This purpose of this article is to discuss the emerging roles of the TRPM7 channel-kinase in various human malignancies, and the potential of exploiting TRPM7 as a cancer biomarker and therapeutic target." (PMID 28379203, 2017). "While it is ubiquitously expressed in normal tissues and cells, TRPM7 is aberrantly over-expressed in various types of malignant neoplasms." (PMID 28379203, 2017). "The chemically induced blockade of TRPM7 expression or its channel activity produces a variety of cellular effects including inhibition of cancer cell survival, proliferation, migration, invasion, and invadosome formation." (PMID 28379203, 2017). "While the functional significance of these mutations remain to be determined, these data suggest the potential of exploiting TRPM7 as a molecular biomarker for prevention, early detection, and prognostication of cancer." (PMID 28379203, 2017). "A decrease in Mg intake reduces intracellular Mg, thus reducing Mg-ATP, in turn increasing cell proliferation by activating Ca channels (TRPM7) which can provide the milieu for development of cancer." (PMID 29093983, 2017). "Hypothetically, aberrantly expressed TRPM7 and dysregulated homeostasis of Mg2+ and Ca2+ in cancer cells modulate the epidermal growth factor (EGF)- or other mitogen-induced signaling pathways." (PMID 28379203, 2017). "Data from a study using mouse xenograft of human cancer show that TRPM7 is required for tumor growth and metastasis." (PMID 28379203, 2017). "Growing evidence has shown that the TRPM7 member plays crucial roles in cellular processes, embryonic development, and human diseases, particularly cancer." (PMID 28379203, 2017). "This suggests the potential value of developing these chemical modulators of TRPM7 into anti-cancer therapeutics." (PMID 28379203, 2017). "These are not only valuable research tools to probe the mechanisms underlying the electrophysiological and cellular functions of TRPM7, but also potential therapeutic agents for various diseases, particularly cancer." (PMID 28379203, 2017). "TRPM7 plays a variety of functional roles in cancer cells including survival, cell cycle progression, proliferation, growth, migration, invasion, and epithelial-mesenchymal transition (EMT)." (PMID 28379203, 2017). "Consistent with the functional roles of TRPM7 in the normal cell types and during organogenesis, numerous studies have shown that TRPM7 regulates cellular proliferation, survival, cell cycle progression, migration, and invasion in cancer cell lines." (PMID 28379203, 2017). "Some of the TRPM7 modulators have been tested in cancer cells, such as a clinically used anesthetic (midazolam), naturally occurring compounds (ginsenoside Rg3, ginsenoside Rd, waixenicin A, carvacrol, and xyloketal B), and the synthetic compound NS8593." (PMID 28379203, 2017). "Abnormal expression of TRPM7 is found in numerous cancers, including colon, implicating TRPM7 in this process." (PMID 28810912, 2017). "The signaling pathways and the mechanisms that mediate the various cellular effects of TRPM7 in cancer cells have been elucidated." (PMID 28379203, 2017).
cancer (continued). "While the functions mediated by TRPM7 in cancer appear to depend on the organ involved, the signaling mechanisms that mediate the functional roles of TRPM7 are related to the cellular and molecular context." (PMID 28379203, 2017). "The broader implication is that endogenous physiological or pathophysiological signaling pathways in GBM that positively modulate TRPM7 would enhance cancer migration and invasion." (PMID 28061441, 2017). "Accumulating evidence has shown that TRPM7 is aberrantly expressed and/or activated in human diseases including cancer." (PMID 28379203, 2017). "Recent studies indicated a close correlation between TRPM7 and cancer, demonstrating its involvement in retinoblastoma, gastric cancer, breast cancer, nasopharyngeal carcinoma, pancreatic cancer, prostate cancer, and ovarian carcinoma." (PMID 27662662, 2016). "After it was reported that disruption of TRPM7 in DT-40 B cell lines affect their survival, evidence has been accumulating for the involvement of TRPM7 in proliferation and metastasis of various forms of cancer cells." (PMID 26149285, 2016). "TRPM7 plays a vital role in embryonic development, anoxia/ischemia, cardiovascular disease, and cancer." (PMID 25913706, 2015). "The role of TRPM7 in cancers is suggested by its up-regulation in the tissues of several cancer types." (PMID 25965832, 2015). "The relevance of TRPM7 for cell proliferation is also evident in other cancers, as genetic suppression of TRPM7 can inhibit the proliferation of human head and neck squamous carcinoma (HNSCC) and ascending aortic vascular smooth muscle cells (VSMC)." (PMID 25277194, 2014). "We will then review the emerging roles of TRPM7 in various types of cancer, and finally discuss its potential as a tumor biomarker and therapeutic target for prevention, early detection, and personalized treatment of malignant diseases." (PMID 25079291, 2014). "There is evidence that TRPM7 is involved in migration, especially in cancer cells and highly migratory fibroblasts." (PMID 25148577, 2014). "Results of studies in culture using cancer cell lines have shown that TRPM7 contributes to cellular proliferation, survival, cell cycle progression, migration, and invasion." (PMID 25079291, 2014). "On the other hand, studies of TRPM7 in diseases, particularly cancer, will help shed new light in the normal functions of TRPM7 under physiological conditions." (PMID 25079291, 2014). "Results of these studies suggest a potential role of TRPM7 as a therapeutic target that can be exploited by using tumor-specific delivery of anti-cancer agents in malignant diseases." (PMID 25079291, 2014). "Transient receptor potential melastatin 7 (TRPM7), a Ca2+-permeable channel, has been demonstrated to be present in cancer cells and involved in their growth and proliferation." (PMID 23426784, 2013). "2-APB, a non-specific TRPM7 inhibitor was also able to mimic the growth-inhibitory activity of midazolam, further supporting the use of TRPM7 as a therapeutic target for cancer." (PMID 23426784, 2013). "The inhibitory effect of waixenicin A was considered to be relatively specific to TRPM7, justifying the high interest of this compound and its analogs in cancer treatment." (PMID 23529027, 2013). "The contributions of TRPM7 to cancer cell migration and tumor metastasis have recently received increasing attention." (PMID 23594099, 2013). "TRPM7 is overexpressed in a variety of human cancer cells such as gastric adenocarcinoma, breast cancer and human head and neck carcinoma cells." (PMID 23529027, 2013). "The present study used midazolam, a benzodiazepine class anesthesic, to pharmacologically intervene in the expression of TRPM7 and to inhibit cancer cell proliferation." (PMID 23426784, 2013). "This suggests the potential of TRPM7 as a valuable target for the pharmaceutical intervention of cancer." (PMID 23426784, 2013). "TRPM7 plays a particularly versatile role in cancer biology." (PMID 40806720, 2025).
cancer (continued). "TRPM6 has been studied less extensively in cancer than TRPM7." (PMID 40003994, 2025). "TRPM7 was overexpressed in NSCLC cell line A549 after stimulation with epidermal growth factor (EGF), with consequent increase in cell migration: both TRPM7-KO and the use of Waixenicin A counteracted the elevation in TRPM7 levels and had anti-cancer stem cell (CSC) effects." (PMID 39940997, 2025). "Ultimately, increased TRPM7 expression significantly contributes to various hallmarks of cancer." (PMID 40003994, 2025). "In addition, single-gene pan-cancer studies have also inspired us, such as the discovery of the broad diagnostic and prognostic value of RAD51, TRPM7, and CENPA in pan-cancer." (PMID 40108724, 2025). "TRPM6 and TRPM7 also have emerging roles in cancer metastasis and oncogenesis." (PMID 40003994, 2025). "Moreover, TRPM7 is overexpressed in many cancers where it regulates cell proliferation, migration and invasion through its channel function, but which also involves its kinase domain." (PMID 41395111, 2025). "Combination of such small GTPase inhibitors with TRPM7 blockers may be proposed as a promising therapeutical strategy to target the oncoprotein complexes involving TRPM7 in cancer cells." (PMID 41395111, 2025). "TRPM7 is a divalent cation-permeable channel that is highly active in cancer cells." (PMID 39513908, 2024). "In addition to the homeostatic control of Mg2+, the TRPM7 channel regulates multiple Zn2+- and Ca2+-regulated pathways pertinent to cancer progression." (PMID 39513908, 2024). "TRPM7 overexpression, intracellular calcium rise, and nuclear stiffening emerge as promising strategies to inhibit the downstream migration of lamin A/Clow cancer cells and, thus, their escape from high-pressure environments, such as the primary tumor." (PMID 39207902, 2024). "Polymorphisms or mutations of TRPM7 have been reported in other types of cancer, but their functional significance in these cancers is not known." (PMID 37445615, 2023). "In two kinds of GC cells, the interference expression of OIP5-AS1/CD147/TRPM7 could induce the apoptosis of cancer cells by down-regulating the expression of BCL-2 and up-regulating the expression of Caspase3, Caspase9 and BAX." (PMID 38156103, 2023). "Deletion of TRPM7 suppressed cancer cell glycolysis and reduced the xenograft tumor burden." (PMID 36878949, 2023). "Of significance, TRPM7 KO considerably inhibited cancer cell proliferation, invasion and migration." (PMID 36878949, 2023). "Hence, our data suggest that block of TRPM7 channel-dependent cellular glycolysis is a novel therapeutic strategy for cancer therapy and pathological angiogenesis." (PMID 36878949, 2023). "Emerging data point to a potential value of TRPM7 as a biomarker and therapeutic target in cancer." (PMID 36768856, 2023). "The mechanosensitivity of TRPM7 channel has been demonstrated in VSMCs and cancer cells." (PMID 36878949, 2023). "To evaluate the effect of the altered expression of the CFA30 genes on cancer cell proliferation, we assessed the proliferation capability of canine MM cancer cells after silencing TRPM7, SPPL2A, GABPB1, and USP8 genes using colorimetric cell proliferation assays." (PMID 35053440, 2022). "In consequence, silencing TRPM7 in PDAC cell lines reduced cancer cell invasion." (PMID 36844925, 2022). "In addition, TRPM7 methylation has been negatively related to metastasis at the lymph node, disease recurrence, and final cancer-induced death." (PMID 36844925, 2022). "However, the role of TRPM6, TRPM7, and TRPM6/7 induced risk of cancer in PPIH model requires further study." (PMID 36110961, 2022). "TRPM7 depletion modulates the de-activation of EMT markers throughout cancer cells." (PMID 35771152, 2022). "Moreover, TRPM7 inhibition decreases MCF-7 cancer cell growth and migration, while MCF-7 cells with MDMX overexpression are more resistant to TRPM7 inhibition-mediated cell migration suppression." (PMID 34627839, 2021).